GATA3 (GATA binding protein 3)
Diseases named in the same sentence as GATA3 in open-access papers (continued):
Sharing a sentence is not in itself a finding about the gene and the disease.
breast carcinoma (continued). "Global gene expression studies pointed to a significant correlation in the overexpression of GATA3 and MUC1 genes commonly observed in breast cancer." (PMID 17078870, 2006). "Indeed, the phenotypic switch from basal-like breast cancer to luminal type can be achieved by re-expressing ERα, FOXA1 or GATA3." (PMID 41318657, 2025). "In March 2023, the patient developed hematuria and was diagnosed with bladder metastasis based on cystoscopy and biopsy, with IHC findings indicating breast cancer origin: ER 90% (1-2+), PR <1%, HER2 (c-erbB-2) 2+, Ki-67 35%, AR 95% (3+), GATA-3+, CK (AE1/AE3)+, and P63-." (PMID 40548112, 2025). "IHC demonstrated positivity for GATA3, ER (60%) and PR (2%), with HER2 negativity and a high proliferation index (Ki-67 70%), findings concordant with the patient’s previous diagnosis of Luminal B, HER2-negative breast cancer." (PMID 41018104, 2025). "In contrast, GATA3, ER, PR, HER2, and SOX10 are important markers for identifying breast cancer." (PMID 41018104, 2025). "For breast cancer, our study highlights that markers extending beyond ER, PR, and HER2—including GATA3, Ki-67, E-cadherin, GCDFP-15, cytokeratin (CK), and mammaglobin—are associated with breast epithelial origin and are commonly utilized as key components of diagnostic panels." (PMID 40313249, 2025). "Immunohistochemistry (TRPS1, GATA-3) and histomorphology (absence of apocrine differentiation) are pivotal for distinguishing accessory breast carcinoma from mimics." (PMID 40978063, 2025). "For instance, notably, the absence of GATA3 expression in ER+ breast cancers is correlated with resistance to hormonal therapy and poor prognosis." (PMID 41514651, 2025). "Although GATA3 is known as a marker for breast cancer, its sensitivity and specificity are not 100%." (PMID 40605856, 2025). "The DNA-binding factor GATA3 is identified and validated as a novel AR interacting protein in breast cancer cells irrespective of ER status." (PMID 38317241, 2024). "Our RIME data identifies GATA3 as a novel AR interacting protein in breast cancer cells irrespective of ER status, indicating that GATA3 can function as a co-regulator of steroid receptors other than ER." (PMID 38317241, 2024). "AR and GATA3 interact to transcriptionally regulate luminal epithelial cell differentiation in breast cancer regardless of ER status." (PMID 38317241, 2024). "TRPS1 negativity in breast carcinomas can lead to difficulties in confirming a breast origin, especially when other breast-specific markers, such as GATA3 or ER, are also absent." (PMID 39518009, 2024). "Moreover, we observed a significant negative correlation between POU4F1 expression and master transcription factors of ER positive breast cancer, such as ESR1, FOXA1 and GATA3, in breast cancer patients from the TCGA and METABRIC cohorts." (PMID 38491910, 2024). "Taken together, these results indicate that GATA3 facilitates but is not essential for AR chromatin binding and implicate GATA3 as an AR co-activator in breast cancer cells." (PMID 38317241, 2024). "This approach revealed the DNA binding, chromatin remodeling factor GATA3 as a fundamental member of the breast cancer AR interactome regardless of disease context." (PMID 38317241, 2024). "Collectively, these data confirm GATA3 as an AR interacting protein in breast cancer cells independent of ER status and suggest a conserved role for this interaction in non-malignant and malignant breast epithelial cells." (PMID 38317241, 2024).
breast carcinoma (continued). "PLA-detected interactions between AR and GATA3 were also evident in clinical primary ER+ /AR + (n = 2 cases) and ER- /AR + (n = 2 cases) breast cancers as well as non-malignant breast tissues from reduction mammoplasties (n = 2 cases)." (PMID 38317241, 2024). "It was based on the immunohistochemical staining results of CK7 positive, CK20 negative, and GATA3 positive, combined with the opinions of multicenter pathologists, showing that the case was finally diagnosed as breast cancer with colon metastasis." (PMID 39943990, 2024). "To determine if a similar phenomenon occurs in the context of ER- breast cancer, we performed AR, GATA3, and H3K27ac ChIP-seq in MDA-MB-453 and MFM-223 breast cancer cell lines treated for 4 h with DHT or a vehicle control after a period of hormone deprivation." (PMID 38317241, 2024). "A recent study observed a gain of DNA methylation at direct GATA3 or FOXA1 binding sites, and validated these two transcription factors mediate hypo-methylated regions, thus resulting in shaping DNA methylation patterns in breast cancer." (PMID 38425344, 2024). "Pathological analysis indicated the presence of metastatic breast cancer, while immunohistochemical studies revealed positive expression of estrogen receptor (ER), GATA-3 and negative expression of progesterone receptor (PR)." (PMID 39286019, 2024). "Like GATA3, FOXA1 is a known ER interacting protein in breast cancer, but unlike GATA3, FOXA1 is essential for ER to bind DNA." (PMID 38317241, 2024). "GCDFP-15 was particularly sensitive to breast lobular carcinoma with high specificity, and GATA-3 was a marker for breast cancer but lacked specificity for CUPAx." (PMID 38750402, 2024). "In addition to GATA3, two other DNA binding transcription factors, JUNB and ERF, were identified as AR interacting proteins in all breast cancer cell line models." (PMID 38317241, 2024). "We noticed that a low level of GATA3 and FOS mRNA predicted poor outcomes for patients with luminal A or B and basal-like subtype breast cancers, and high FOSL1 expression also predicted a poor outcome for patients with luminal A subtype breast cancers." (PMID 37353480, 2023). "In terms of immunohistochemical surveys, ER and GATA3 positivity and caudal type homeobox 2 (CDX2) negativity may support the diagnosis of gastrointestinal metastases from breast cancer." (PMID 37845365, 2023). "GATA3 is a sensitive and relatively specific biomarker of urothelial and breast carcinomas, while most Müllerian carcinomas are GATA3-negative." (PMID 39516338, 2023). "A study has revealed that GATA3 expressed in 100% of luminal A and luminal B breast carcinomas, and in 43% of triple‐negative breast cancers." (PMID 36281523, 2023). "As a marker, absent or low GATA-3 expression in either, human breast cancer and murine models of luminal breast cancer, indicate a loss of cell differentiation, propensity for invasive growth, and development of distant metastases." (PMID 37483298, 2023). "Notably, GRHL2 can regulate ER⍺ signaling output in hormone receptor positive breast cancer by co-occupying enhancer elements with FOXA1, GATA3, and ER⍺." (PMID 36691073, 2023). "This cohort contained a subset of genes that could be considered potential biomarkers for breast cancer progression, including FOXA1, MLPH, ESR1, AR, GATA3, TFF1, THSD4, and TBC1D9." (PMID 38020889, 2023). "Based on the published interaction of GRHL2 with ER⍺, FOXA1, and GATA3 at enhancer elements of target genes, we addressed to what extent the identified conserved GRHL2 binding sites in luminal breast cancer cells were flanked by putative binding sites for the ER⍺-mediated transcriptional complex." (PMID 36691073, 2023). "In the current study, MGP was rarely expressed in lung adenocarcinomas (0.7%), which is lower than the previously reported positivity of GATA3 (∽8%,) and TRPS1 (2–3%,), indicating that MGP is a good marker to differentiate breast cancer from lung adenocarcinoma." (PMID 36284362, 2022).
breast carcinoma (continued). "When combining GATA3, TRPS1, and MGP, we observed that 797/1201 (66.4%) of the enrolled breast carcinoma cases were positive for all three markers, including 452/565 (80.0%), 238/352 (67.6%), and 107/284 (37.7%) in the ER/PR+, HER2+, and TNBC subgroups, respectively." (PMID 36284362, 2022). "Furthermore, GATA3 regulates THSD4 expression and promotes the transition of normal cells into breast cancer through THSD4 dysregulation." (PMID 35498536, 2022). "Finally, we validated our predictions in breast cancer cells and showed that FOXA1 and GATA3 indeed mediate DNA hypo-methylation." (PMID 35331302, 2022). "The FOXA1 gene, which opposes SOX10 expression, cooperates with ER1 to maintain luminal identity in breast cancer, whereas GATA3, XBP1, and CA12 showing a negative correlation with SOX10, also cooperate in ER1 signaling." (PMID 36496864, 2022). "A similar result was obtained when using a six-gene (AGR2, SLC44A4, TBC1D9, FOXA1, GATA3, and CA12) breast cancer steroid response module (Kruskal-Wallis p = 0.01 across all patients, p = 0.94 in HRDetect-high patients, and p = 0.02 in HRDetect-low/intermediate patients)." (PMID 33568222, 2021). "It has been previously reported that the pioneers TFs FOXA1 and GATA3 mediated ESR1 binding by shaping enhancer accessibility; FOXA1 collaborates with GRHL2 and MLL3 to establish a targetable collateral pathway in endocrine therapy-resistant breast cancer." (PMID 34395436, 2021). "In ER-positive breast cancer cell lines, enrichment in GATA motifs was observed in ERα and FOXA1 ChIP-Seq/Exo peaks and GATA3 silencing decreased or even abolished the recruitment of ERα at distal regulatory regions normally co-occupied with GATA3." (PMID 34831189, 2021). "Above all, GATA-3 has been reported that its expression is induced during fracture healing and many studies have reported the correlation between the GATA-3 and estrogen receptor in breast cancers as well." (PMID 33800915, 2021). "Reduction of SPRY4 expression, for example, increases cancer stem cell properties in MDA-MB-231 cells, while reduced expression of FOXA1 and GATA3 by inhibiting the mitogen-and stress-activated protein kinase (MSK1) enhances the metastatic progression of ER + breast cancer." (PMID 34238359, 2021). "We then performed immunostaining for these human breast cancer samples and found that in the ER-positive group, BRCA1-positive tumors whose BRCA1 mRNA levels were equal to or higher than 1.5 expressed moderate to strong GATA3 protein." (PMID 34373738, 2021). "Of note, reduced GATA3 expression is often seen in the luminal B breast cancer subtype but not in luminal A." (PMID 34561764, 2021). "GATA3 and FOXA1 are marker genes that define an ESR1-positive breast cancer." (PMID 34395436, 2021). "ESR1, FOXA1, GATA3, and EP300 TFBSs were enriched in CCVs for overall breast cancer." (PMID 34439109, 2021). "Although deletion of p18 stimulates expression of DNMT1 in MECs and stromal cells, mice lacking p18 develop Gata3-positive well-differentiated mammary tumors." (PMID 34373738, 2021). "Despite upregulation of GATA3 and significant changes in lineage marker profiles towards a luminal epithelial fate, the claudin-low mammary cancer cells did not complete a mesenchymal-epithelial transition (MET)." (PMID 34145248, 2021). "Another study by Mertins and colleagues on breast cancer showed that despite a C-terminal truncation of GATA3, its protein expression level did not decrease, suggesting the occurrence of post-translational modification." (PMID 32860207, 2020).
breast carcinoma (continued). "Furthermore, either miR-433-3p overexpression or GATA3 knockdown impaired the effects of GNAS-AS1 on M2 macrophage polarization and ER+ breast cancer cells progression." (PMID 32538432, 2020). "This priority list includes established breast cancer driver genes such as MYC and GATA3 but also includes many genes with no reported role in breast cancer." (PMID 31910858, 2020). "In breast cancer metastases, FOXA1 expression was associated with Nestin-negativity, GATA3-positivity, ER-positivity, HER2-positivity and non-triple-negative status (P < 0.05)." (PMID 30819139, 2019). "GATA binding protein 3 (GATA3), a transcription factor that regulates normal cell differentiation, serves as a biomarker of luminal epithelial cells and is involved in the progression of breast cancer 5-7." (PMID 31754326, 2019). "Indeed, forced expression of wild-type BRCA1 in breast cancer cell lines silenced FOXC1, whereas GATA3 knockdown induced its expression." (PMID 30764547, 2019). "Though it is widely accepted that GATA3 is a tumor suppressor, the detailed mechanism repressing the progression of breast cancer is not entirely clear." (PMID 31754326, 2019). "The percentage of GATA3 negative breast cancers vary from study to study, ranging from 0 to 46% in ER positive tumors and from 17 to 97% in estrogen negative cancers." (PMID 31718619, 2019). "In summary, our analysis results show that GATA3, UTX, and Dicer are downregulated in breast cancer, and UTX and Dicer might represent potential breast cancer biomarkers." (PMID 31685800, 2019). "In summary, this study revealed that GATA3 recruits the UTX to form a complex in breast cancer cells, which provides new insights into how the UTX selects its interacting transcription factors in breast cancer cells." (PMID 31685800, 2019). "Several frequently mutated genes in breast cancer, such as CDH1, GATA3, and MAP3K1, were not mutated in any MPA/DMBA-induced tumors." (PMID 31366361, 2019). "Clinicopathological characterization of CK7 negative breast cancer has not been addressed previously and similar studies on GATA3 negative tumors are limited." (PMID 31718619, 2019). "The GATA3 expression was different in Luminal A versus TNBC and Luminal B versus TNBC, and its expression level was the higher in ER-positive breast cancer than other breast cancer subtypes." (PMID 30866472, 2019). "GATA3 is a master TF that induces mammary luminal differentiation and is usually not expressed in basal-like breast cancers." (PMID 31013830, 2019). "The mainly purpose of the study is to understand the pathobiology of the CK7 negative and GATA3 negative breast cancer." (PMID 31718619, 2019). "We utilized the GEO GEO2R tool to analyze differentially expressed genes between MDA-MB-231 breast cancer cell lines that overexpressed or did not overexpress GATA3." (PMID 31754326, 2019). "Cytokeratin 7 (CK7) and GATA binding protein 3 (GATA3) are considered as immunohistochemical hallmarks of breast cancers; however, there are breast tumors lacking these markers." (PMID 31718619, 2019). "Our results show that the GATA3-UTX-Dicer axis is involved in breast cancer metastasis, and further that elevated expression of GATA3, UTX, and Dicer is correlated with favorable prognosis in breast cancer." (PMID 31685800, 2019). "When a primary breast cancer is suspected, TTF1 and GATA3 are the most relevant markers." (PMID 29881714, 2018). "Additionally, TiHo-0906 cells at low and high passage also displayed CNGs in regions harbouring other known breast cancer-related genes like FOXO3 and MYB (FCA B2), AKT1 (FCA B3), and GATA-3, CCND2, CDK4 and PFDN5 (FCA B4)." (PMID 30185896, 2018). "Thirty consecutive cases of male breast cancer and eight loco-regional metastases were re-revaluated, assembled in tissue micro array (TMA), and stained with immunohistochemistry (IHC) for NY-BR-1, GATA-3, mammaglobin, and BRST-2." (PMID 29116378, 2018).
breast carcinoma (continued). "Moreover, using a reporter assay and a ChIP assay, our study demonstrates that Notch3 is capable of binding to CSL-binding motifs in the promoter of GATA-3 in breast cancer cells, suggesting that N3ICD directly activates GATA-3 expression." (PMID 30100605, 2018). "Similar to GATA-3, this marker does not exclusively label breast cancer: it is expressed by apocrine glands, including those in the breast, the tracheobronchial tree, sweat gland carcinomas, and salivary gland carcinomas." (PMID 29116378, 2018). "Furthermore, breast cancers frequently express mammaglobin, gross cystic disease fluid protein-15 (GCDFP15), and trans-acting T-cell-specific transcription factor (GATA3)." (PMID 29881714, 2018). "We used MDA-MB-231-N3ICD cells to investigate the function of the Notch3/GATA-3 axis in distant spreading of breast cancer, with/without GATA-3 knockdown, in tumor xenograft models." (PMID 30100605, 2018). "One of the typical members of the GATA family, GATA3, was reported to interact with G9A/NuRD(MTA3) to suppress breast cancer metastasis through targeting the promoters of an array of genes involved in important cellular signaling pathways regulating cell migration and invasion." (PMID 30563971, 2018). "In this study, we showed that expression of the pro-inflammatory cytokine IL-20 was regulated by a transcriptional complex composed of the transcription factors ER(α), GATA3, and FOXA1 and the transcriptional elongation factor Ell3 in ER(+) breast cancer cells." (PMID 28514748, 2017). "Several Gata3 target genes have been proposed, including CCND1, CDKN2C, MUC1, and ESR1, however the target genes affected by Gata3 mutations in human breast cancers have not been elucidated." (PMID 29262572, 2017). "Although there has been no report of GATA3 in vulvar adenocarcinoma of mammary-like glands, it is conceivable that the vast majority of these tumors will be positive for GATA3 as in breast carcinoma." (PMID 28693610, 2017). "Other useful markers include mammaglobin and GATA3 (usually positive in breast carcinoma and negative in ovarian carcinoma)." (PMID 28730323, 2017). "In addition, CCLE analysis was consistent with that of ONCOMINE demonstrating that GATA3 and TRPS1 were distinctively up-regulated in breast cancer cell lines, while other GATA members were present at a low transcription level or absent in breast cancer cells." (PMID 28423734, 2017). "Therefore, we examined expression of ELK3, GATA3, and LOX by constructing a heat map matrix using public microarray data derived from breast cancer cell lines." (PMID 27556500, 2016). "GATA3 and RP56KB1 are two promising drug targets for breast cancer." (PMID 27556158, 2016). "Similar to NUMB, the EMT negative regulators GATA3 and FOXA1 had significantly lower expression in the BLBC subtypes, ER-negative and higher histological grade breast cancer patients, while the EMT inducers FOXC1, FOXC2 and SNAI1 mimicked the expression profiles of Notch1." (PMID 27506933, 2016). "In the previous studies of breast cancer which set cutoff value according to IHC positivity, there is no consistency in determining GATA3 positivity among the studies." (PMID 27249072, 2016). "Interestingly, the GATA3 down-regulation is required for the progestin-induced upregulation of cyclin A2(CCNA2) and for progestin-induced in vivo and in vitro breast cancer cell growth." (PMID 27454576, 2016). "Luminal markers, ERα and GATA3 were only expressed in MCF-7 but not in the basal-type breast cancer lines." (PMID 27043660, 2016). "Similar to NUMB, the EMT negative regulators GATA3 and FOXA1 had significantly lower expression in the BLBC subtypes and in ER-negative and higher histological grade breast cancer patients, whereas the EMT inducers FOXC1, FOXC2 and SNAI1 mimicked the expression profile of Notch1." (PMID 27506933, 2016).